NME2P2 (NME2 pseudogene 2)
Gene: Processed pseudogene on chromosome 2 (47,705,468 to 47,705,979, forward strand). Ensembl gene ENSG00000224443.
Diseases named in the same sentence as NME2P2 in open-access papers:
NME2P2 is named in the same sentence as 2 diseases in open-access papers, as found by Europe PMC text mining. Sharing a sentence is not in itself a finding about the gene and the disease. The quoted sentences say what the papers report.
cancer (1 paper, 2023). A tumor composed of atypical neoplastic, often pleomorphic cells that invade other tissues. "Some are known to be tumor suppressor genes (OPCML-IT2), to be related to resistance to cancer therapies (RAC1P3), or to be involved in several cancer processes such as genome stability (XRCC6P2), tumor growth and metastasis (MIR602) and regulation of gene transcription (NME2P2)." (PMID 36647008, 2023).
NME2P2 also shares sentences with these, for which no sentence is quoted: tumor (1 paper).